IL12A (interleukin 12A)
Description:
Heterodimerizes with IL12B to form the IL-12 cytokine or with EBI3/IL27B to form the IL-35 cytokine. IL-12 is primarily produced by professional antigen-presenting cells (APCs) such as B-cells and dendritic cells (DCs) as well as macrophages and granulocytes and regulates T-cell and natural killer-cell responses, induces the production of interferon-gamma (IFN-gamma), favors the differentiation of T-helper 1 (Th1) cells and is an important link between innate resistance and adaptive immunity. Mechanistically, exerts its biological effects through a receptor composed of IL12R1 and IL12R2 subunits. Binding to the receptor results in the rapid tyrosine phosphorylation of a number of cellular substrates including the JAK family kinases TYK2 and JAK2. In turn, recruited STAT4 gets phosphorylated and translocates to the nucleus where it regulates cytokine/growth factor responsive genes. As part of IL-35, plays essential roles in maintaining the immune homeostasis of the liver microenvironment and also functions as an immune-suppressive cytokine (By similarity). Mediates biological events through unconventional receptors composed of IL12RB2 and gp130/IL6ST heterodimers or homodimers. Signaling requires the transcription factors STAT1 and STAT4, which form a unique heterodimer that binds to distinct DNA sites.
Synonyms: IL-12A; NKSF1; CLMF; p35; NFSK
Tractability: Antibody: UniProt places it where antibodies can reach, with high confidence; its Gene Ontology location is reachable by antibodies, with high confidence; UniProt predicts a signal peptide or a membrane-spanning region.
Safety:
Unwanted effects reported when the protein is acted on. In parentheses: how it was acted on, where the effect was seen, and who reports it.
anemia (source: ClinPGx)
Gene: Protein-coding gene on chromosome 3 (159,988,835 to 159,996,019, forward strand). Ensembl gene ENSG00000168811.
Subcellular location: Secreted
Pathways (Reactome):
Immune System: Interleukin-10 signaling; Interleukin-12 signaling; Interleukin-35 Signalling; Interleukin-4 and Interleukin-13 signaling
Gene Ontology:
Molecular function: cytokine activity; growth factor activity; interleukin-12 beta subunit binding; interleukin-27 binding; protein binding; protein heterodimerization activity; interleukin-12 receptor binding
Biological process: cell migration; cellular response to virus; defense response to Gram-positive bacterium; extrinsic apoptotic signaling pathway; interleukin-12-mediated signaling pathway; negative regulation of blood vessel endothelial cell proliferation involved in sprouting angiogenesis; negative regulation of interleukin-17 production; negative regulation of protein secretion; negative regulation of smooth muscle cell proliferation; negative regulation of vascular endothelial growth factor signaling pathway; positive regulation of cell adhesion; positive regulation of dendritic cell chemotaxis; positive regulation of lymphocyte proliferation; positive regulation of mononuclear cell proliferation; positive regulation of natural killer cell activation; positive regulation of natural killer cell mediated cytotoxicity; positive regulation of natural killer cell mediated cytotoxicity directed against tumor cell target; positive regulation of NK T cell activation; positive regulation of smooth muscle cell apoptotic process; positive regulation of T cell mediated cytotoxicity; positive regulation of type II interferon production; positive regulation of tyrosine phosphorylation of STAT protein; response to lipopolysaccharide; response to UV-B; response to virus; and 4 more
Cellular component: extracellular region; interleukin-12 complex; interleukin-35 complex; endoplasmic reticulum lumen; late endosome lumen; receptor complex; cell surface; cytoplasm
Genetic constraint (gnomAD): Loss-of-function variants: 13 observed, 18.26 expected, observed/expected ratio (o/e) 0.71, 90% interval 0.46 to 1.13. The upper end of that interval is the gene's LOEUF score, 1.13, which puts it in group 4 of 6, group 1 being the genes least tolerant of losing a copy. Missense variants: 206 observed, 245.95 expected, observed/expected ratio (o/e) 0.84, 90% interval 0.75 to 0.94. Synonymous variants: 76 observed, 90.67 expected, observed/expected ratio (o/e) 0.84, 90% interval 0.7 to 1.01.
Homologues: Orthologues: chimpanzee IL12A (99% identical), macaque IL12A (94% identical), dog IL12A (85% identical), pig IL12A (84% identical), guinea pig IL12A (73% identical), rabbit IL12A (73% identical), rat Il12a (59% identical), mouse Il12a (59% identical), zebrafish zmp:0000001127 (22% identical), zebrafish il12a (19% identical).
Diseases named in the same sentence as IL12A in open-access papers:
IL12A is named in the same sentence as 140 diseases in open-access papers, as found by Europe PMC text mining. Sharing a sentence is not in itself a finding about the gene and the disease. The quoted sentences say what the papers report.
colitis (10 papers, 2015 to 2024). Inflammation of the colon. "The colitis mice given a neutralizing S100a9 antibody produced less inflammatory cytokines, such as Tnfα, Il1β, Il6, Il17a, Ifnγ, and Il12a, all of them are master regulators of inflammation and tumorigenesis." (PMID 29326691, 2017). "Our results indicated that the absence of myeloid STING significantly decreased the levels of Il12b, Il12a, and Il23a in colitis and the deletion of STING in DMXAA-treated BMDMs/BMDCs noticeably suppressed pathways related to the IL-12 family and IL-12/IL-23 production." (PMID 39113810, 2024). "The observed reduction of IL12A mRNA by atorvastatin and rosuvastatin is in line with previous findings indicating that rosuvastatin (0.3 mg/kg/day; 21 days) can significantly reduce the serum level of IL-12 in mice with colitis induced by dextran sulfate sodium (DSS)." (PMID 36753488, 2023). "The S. verbenaca-treated group showed a marked downregulation in the mRNA expression of Il-1β, Il-6, Il-12a and Il-23 (p < 0.05 vs. colitic control group), thus confirming the amelioration in the colonic inflammatory status exerted by the extract in this experimental model of colitis." (PMID 38136191, 2023). "In contrast, CD11c+ cells from DC-LMP1/CD40xRag1−/−-mice that do not develop colitis do not express elevated levels of Il23a, Il12a, il1b." (PMID 28276457, 2017). "It is noteworthy that LPS-induced production of IL-12a, IL-12b, IL-23a, and IL-6 mRNA was not suppressed in colon CD11c+ DCs from Wnt5aMxΔ/Δ mice, which are consistent with the observation that Wnt5aMxΔ/Δ mice showed the phenotypes similar to control mice in DSS-induced colitis." (PMID 26030277, 2015).
COVID-19 (9 papers, 2021 to 2025). A disease caused by infection with severe acute respiratory syndrome coronavirus 2. "However, IL12RB1 and IL12RB2 transcript levels as well as those encoding for the cytokines, IL15 and IL12 (IL15 and IL12A, respectively) decreased in life-threatening COVID-19 and MIS-C." (PMID 41285788, 2025). "We consecutively included patients during the first peak of the COVID-19 epidemic in Brazil and analyzed the expressions of genes encoding interleukin (IL)-1β, IL-6, IL-8, IL-10, IL-12A, IL-12B, and tumor necrosis factor-α in peripheral blood mononuclear cells." (PMID 33819170, 2021). "Initially, we assessed the expression of IL6, IL12A, and TNFA, which are key pro-inflammatory genes implicated in the cytokine storm associated with COVID-19." (PMID 41583455, 2025). "In particular, we observed increase inthe levels of cytokines known to contribute to cytokine storms as IL-1β, IL-6, IL-12A, IL-12B, IFN-γ, and TNF-α as well as various chemokines and CSFs upon infection with the COVID-19 variants." (PMID 39759510, 2024). "Hematologic cancer patients that showed highly networked and coordinated anti-SARS-CoV-2 antibody production, with central importance of IL-4, IL-5, IL-12A, IL-15, and IL-17A, presented only mild COVID-19." (PMID 36700209, 2022). "Specifically, we found that the expression of genes encoding proinflammatory cytokines (IL12B, IL15, IL6, IL12A and IL1B) and chemokines (CXCL9, CXCL11 and CXCL10) was broadly increased in COVID-19 patients and speculate that other viral infections may also induce expression of these genes." (PMID 33780352, 2021). "Our results revealed that serum from patients with severe COVID-19 significantly upregulated IL6 and IL12A expression in HUVEC within 60 min of stimulation." (PMID 41583455, 2025). "However, IL15, CXCL9 and IL12A levels were not significantly altered in KD or severe COVID-19 compared to FC or HC, respectively." (PMID 36159873, 2022). "Data collected revealed that circulating NKT from COVID-19 patients produced significantly less IFN-γ but more IL-17 compared with cells from healthy donors even if these cytokines were more represented in ETAs than plasma, and decreased the production of IL-12A and IL-10 compared to control." (PMID 35159352, 2022).
asthma (8 papers, 2008 to 2020). "We are interested in the association between IL-12A and IL-12B genotypes and asthma-relevant phenotypes." (PMID 28600552, 2017). "In this hospital-based case-control study, we investigated the association of IL-12A rs568408, IL-12A rs2243115 and IL-12B rs3212227 polymorphisms and risk of asthma in Taiwan." (PMID 28600552, 2017). "The A allele at IL-12A rs568408 was associated with increased risk of asthma, compared to the G allele (OR = 1.63, 95% CI = 1.19–2.23, P = 0.0021)." (PMID 28600552, 2017). "The aim of this study was to investigate the association of polymorphisms in IL-12A/IL-12B with asthma." (PMID 28600552, 2017). "In the current study, we identified a molecular risk biomarker, the AA genotype at IL-12A rs568408, for asthma susceptibility in early detection and prediction." (PMID 28600552, 2017). "As for gender analysis, the A allele at IL-12A rs568408 was significantly higher in the asthma group than the control group among women (P = 0.0131), but not significant among men (P = 0.0593)." (PMID 28600552, 2017). "The gene for IL12A (IL12A) is located on chromosome 3p12-13.2, a genomic region linked to asthma and its intermediate phenotypes." (PMID 18671862, 2008). "Among children with asthma in two ethnically distinct cohorts, SNPs in IL12A were associated with an increased risk of sensitization to cockroach but not with asthma or other objective markers of atopy (serum total IgE, STR or IgE to dust mite)." (PMID 18671862, 2008). "In summary, this study demonstrates that polymorphisms in IL12A are associated with sensitization to cockroach among children with asthma." (PMID 18671862, 2008). "In stratified analyses by age, it appeared that the allelic frequencies of the A allele at IL-12A rs568408 was significantly higher in the asthma group than the control group among people of less than 37.7 years old (P = 0.0007), but not among people at the age ≥37.7 years old (P = 0.3876)." (PMID 28600552, 2017). "In 2011, Chen and colleagues reported that IL-12A rs568408 and IL-12B rs3212227 SNPs may individually and jointly contribute to asthma risk in a moderate population, 197 asthma patients and 369 controls in mainland China23." (PMID 28600552, 2017). "Thus, it is worthwhile for scientists to investigate the gene-gene interaction between IL-12A and IL-12B and their possibility to be novel determinants for asthma susceptibility, as is the case for cancer genomic etiology." (PMID 28600552, 2017). "IL-12A polymorphisms have been associated with the development of several diseases, such as rheumatoid arthritis, Alzheimer's disease, Graves' disease, and asthma." (PMID 28321150, 2017). "Therefore, in the current study, IL-12A rs568408, IL-12A rs2243115, and IL-12B rs3212227 polymorphisms were selected to investigate the associated risk of asthma in Taiwan, and their associations with clinical features, such as symptoms severity." (PMID 28600552, 2017). "The current study found that A allele at IL-12A rs568408 may act as a recessive determinant to asthma etiology and symptoms severity." (PMID 28600552, 2017). "Thus, we performed a study of association between variants in IL12A and asthma and allergy-related phenotypes in families of children with asthma in an ongoing study of the Genetics of Asthma in Costa Rica." (PMID 18671862, 2008). "Our findings suggest that variants in IL12A influence cockroach allergy among children with asthma." (PMID 18671862, 2008). "However, there are only limited studies to date that have examined the association between IL-12B genotypes and asthma risk, and the contribution of IL-12A genotypes to asthma is largely unknown." (PMID 28600552, 2017). "Thus, our findings for IL12A may be due to a more marked influence of variants in this gene on cockroach sensitization than on other allergy phenotypes among children with asthma." (PMID 18671862, 2008).
asthma (continued). "Moreover, DAPP1 expression in the lung was highly positively correlated with a panel of pro-inflammatory cytokines, including several that have been implicated in asthma, such as IL1A, IL7, IL12A, IL17A, IL23A, and IL33." (PMID 31869344, 2019). "In the near future, our findings could be validated in other asthma populations to determine if the AA IL-12A rs568408 genotype is a common genomic biomarker for asthma in these populations." (PMID 28600552, 2017). "We found that SNPs at IL-12A rs568408, but not IL-12A rs2243115 or IL-12B rs3212227, were genomic determinants for asthma risk." (PMID 28600552, 2017). "The AA genotype [odds ratio (OR) = 3.50, 95% confidence interval (CI) = 1.57–7.82, P = 0.0022], but not AG (OR = 1.28, 95% CI = 0.86–1.91, P = 0.2175), at IL-12A rs568408 demonstrated a statistically significant risk for asthma in Taiwan." (PMID 28600552, 2017). "Because age and gender may play a role in asthma, we were also interested in the interaction of the IL-12A rs568408 genotype with age and gender of the participants." (PMID 28600552, 2017). "The association between IL12A polymorphisms and cockroach allergy but not asthma is consistent with results from human studies of recombinant IL12." (PMID 18671862, 2008). "Some C3 proteins are highly associated with asthma, such as: CD80 influences synthesis of IL-4 and IFN in non-specific bronchial asthma, mutations in IL12A influence cockroach allergy among children with asthma, ADA polymorphisms are related to asthma." (PMID 33008305, 2020).
autoimmune disease (7 papers, 2007 to 2025). A disorder resulting from loss of function or tissue destruction of an organ or multiple organs, arising from humoral or cellular immune responses of the individual to their own tissue constituents. "IL12A is associated with Ustekinumab, Ebdarokimab, and Briakinumab, which are employed in the treatment or research of psoriasis and various autoimmune diseases." (PMID 38997544, 2024). "As far as we know, this is the first study explored about the associations between IL-35 gene single nucleotide polymorphisms and the genetic susceptibility to autoimmune diseases, in which IL-35 encoding genes, IL-12A and EBI3, were analyzed together." (PMID 31013577, 2019). "Similar with the locus RGS1, IL12A has been reported with risk of MS and T1D, confirming the shared genetic factors among different autoimmune diseases." (PMID 27043536, 2016). "Interestingly, this was also predicted as a causal variant by a sequence-based predictor of regulatory variants, and is an eQTL for IL12A, a cytokine implicated in several autoimmune diseases." (PMID 30650056, 2019). "Four genes (BLK, HSPA1A, IL12A, NEU1) have been targeted for drug development in autoimmune diseases and other conditions." (PMID 38997544, 2024). "Pro-inflammatory cytokines, such as TNF or IL12A, the T-cell activation molecule CD28, the regulatory molecules IL10, TGFB1 or the adhesion molecules ITGA4 and ITGB1 have all been evaluated previously as therapeutic targets for autoimmune diseases, including MS." (PMID 18030350, 2007).
glioma (7 papers, 2016 to 2025). A benign or malignant brain and spinal cord tumor that arises from glial cells (astrocytes, oligodendrocytes, ependymal cells). "We also observed a strong association of IL12A expression with low EMT score in Brain Lower-Grade Glioma (LGG, p < 0.001) and Glioblastoma Multiforme (GBM, p < 0.01) cancer types." (PMID 35096592, 2021). "Amplified IL-12A and IL-12B gene expression profiles were also observed in human high-grade glioma samples compared to the controls." (PMID 41034696, 2025). "The transcript levels of IL12A/B in recurrent glioma were comparable with de novo tumors and independent of glioma grade." (PMID 40842154, 2025). "The data shown in our study indicate that overexpressed JMJD1C increases the expression of M1 markers (IL‐1β, TNF, CXCL9, IL‐23, ROS1, IL‐12a, and IL‐12b) both in the glioma mouse models and in the CD14+ monocytes co‐cultured with glioma cells." (PMID 34586733, 2021). "In microglia sorted from rat C6 gliomas, genes characteristic for M1 activation: Tlr2, Tlr4 and Il18, Cd80, Il12a, Il15 were significantly downregulated." (PMID 29242629, 2017).
psoriasis (6 papers, 2009 to 2024). An autoimmune condition characterized by red, well-delineated plaques with silvery scales that are usually on the extensor surfaces and scalp. "In lesional skin of patients with psoriasis, p35 (IL-12A) transcripts were not increased, whereas p40 (IL-12B) and p19 (IL-23A) transcripts were increased." (PMID 36110854, 2022).
viral infection (6 papers, 2011 to 2023). "Most overexpressed proteins are involved in immune response, as T-cells activation and functions (CD59, IL12A) or the response to bacterial and viral infections (CTSD, TRIM22)." (PMID 25594007, 2014). "However, some of these proteins also are involved in immune response and inflammation, as T-cells function and activation (CD59, IL12A); others are involved in the response to bacterial and viral infections (CTSD, TRIM22)." (PMID 25594007, 2014). "We also noticed that the expression of Ccl5 and Il12a/Il12p70 reached the peak on 5 d.p.i., which could reflect the activation of T and natural killer (NK) cells during viral infection (p = 0.0050 for Ccl5 in C57BL/6, p < 0.0001 for Il12a/Il12p70 in BALB/c and C57BL/6)." (PMID 34907154, 2021).
Autoimmunity (5 papers, 2012 to 2025). The occurrence of an immune reaction against the organism's own cells or tissues. "Genetic risk factors have been newly identified for Sjögren’s syndrome, including IRF5, STAT4, CXCR5, IL12A, HLA-DRA, and BLK, which are linked to autoimmune disorders as well." (PMID 40136761, 2025).
primary biliary cirrhosis (5 papers, 2014 to 2022). "IL12A has an immunomodulatory effect, is significantly involved in the susceptibility to primary biliary cholangitis, and can be used as a molecular target for clinical diagnoses." (PMID 35141308, 2021). "Rs4679868 A and rs9852519T alleles (both in IL-12A) have been associated with increased risk of primary biliary cirrhosis whereas the A allele of rs6131 (SELP) has been found to lower platelet activation upon release of the cross-clamp in patients undergoing coronary artery bypass graft." (PMID 26396182, 2015). "The two seed genes in this cluster are the cytokine subunit IL12A and its receptor subunit IL12RBA, previously implicated in the primary biliary cirrhosis, while the two detected connectors consist of other subunits for the IL12 cytokine and its receptor." (PMID 36458021, 2022). "Notably, a recent GWA study of primary biliary cirrhosis revealed an association with IL12RB2, IL12A (a gene encoding for the p35 subunit of the IL-12 cytokines) and STAT4 (downstream of IL12RB2)." (PMID 24586521, 2014).